GPR171 (G protein-coupled receptor 171)
Diseases named in the same sentence as GPR171 in open-access papers (continued):
Sharing a sentence is not in itself a finding about the gene and the disease.
tumor (4 papers, 2016 to 2025). "It has been shown that GPR171 is a pro-oncogene that induces proliferation, invasion, and migration of tumor cells." (PMID 36212434, 2022). "When we delayed the treatment to 10 days post tumor inoculation, we were still able to see a significant delay of tumor growth by GPR171 antagonist, accompanied with extended mouse survival." (PMID 34615877, 2021). "GPR171 blockade promotes antitumor immunity to inhibit tumor progression and offers a target for cancer immunotherapy." (PMID 34615877, 2021). "As a result, tumor weights in GPR171lacZ/lacZ mice after 16 days inoculation were less than 1/3 of those from WT or GPR171+/LacZ littermates." (PMID 34615877, 2021). "The delayed treatment of GPR171 antagonist or TIGIT mAb alone had minimal effects on slowing down tumor progression; however, GPR171 antagonist displayed a great synergy with anti-TIGIT to inhibit CT26 tumor growth, so as to extend mouse survival." (PMID 34615877, 2021). "In both tumor models, GPR171 blockade proportionally increased intratumoral CD3+ T cells and CD8 + T cells in CD45+ immune cells and increased the ratio of CD8+ to CD4+ T cells within tumors." (PMID 34615877, 2021). "The treatment of PD-L1 mAb or GPR171 antagonist alone modestly slowed down tumor growth while the combination of these two agents markedly inhibited tumor growth." (PMID 34615877, 2021). "We inoculated GPR171lacZ/lacZ and littermates with MC38 tumors subcutaneously to assess the effect of GPR171 signaling on tumor immunity." (PMID 34615877, 2021). "Taken together, our results support that blockade of GPR171 signaling improves ICB therapy against cancer in several mouse tumor models." (PMID 34615877, 2021). "GPR171+/lacZ mice and WT mice displayed comparable tumor growth curves while tumor growth was significantly retarded in GPR171lacZ/lacZ mice." (PMID 34615877, 2021). "In a therapeutic mouse model of MC38, we started with the treatment of a PD-L1 mAb and GPR171 antagonist 10 days after tumor inoculation when all tumors had grown over 150 mm3." (PMID 34615877, 2021). "In both tumor models, the treatment of GPR171 antagonist right after tumor cell inoculation was able to slow down tumor growth and thereby reduce tumor weight." (PMID 34615877, 2021). "Taken together, our data suggest that GPR171 inhibition promotes a T-cell -mediated anti-tumor immunity." (PMID 34615877, 2021). "Therefore, our findings support that the BigLEN/GPR171 axis can be important in inhibiting tumor immunity." (PMID 34615877, 2021). "However, the inclusion of GPR171 antagonist together with ICB significantly slowed down B16F1 tumor growth and extended mouse survival." (PMID 34615877, 2021). "We dissected tumor tissues to further determine the impact of GPR171 blockade on the TIME." (PMID 34615877, 2021). "Thus, the enrichment of GPR171 expression in TILs implies an important role of GPR171 in tumor immunity." (PMID 34615877, 2021). "Our study supports GPR171 as a T-cell checkpoint important for tumor immunity." (PMID 34615877, 2021). "In cluster 1 (pyr-0), genes, including GPR171 and NLRC3, regulate pathways related to tumor occurrence and development, such as cell-substrate adhesion." (PMID 39744500, 2025). "In draining lymph nodes (dLNs), there was a small percentage of GPR171-positive T cells, which were presumably tumor-reactive T cells; over half of intratumoral T cells, including both CD4+ and CD8+ T-cell subsets, expressed GPR171." (PMID 34615877, 2021).
cancer (3 papers, 2014 to 2021). A tumor composed of atypical neoplastic, often pleomorphic cells that invade other tissues. "Together, our study identifies the GPR171/BigLEN axis as a T cell checkpoint pathway that can be modulated for cancer immunotherapy." (PMID 34615877, 2021). "All these warrant a further comprehensive investigation into the role of GPR171 in ICB efficacy of cancers in the clinic." (PMID 34615877, 2021). "On the other hand, GPR171 is a well-accepted T-cell signature gene in cancer database analysis, though its potential immune function is untested." (PMID 34615877, 2021). "In line with that, GPR171 expression is well associated with T-cell signature genes CD3e and LCK across multiple cancer types in The Cancer Genome Atlas (TCGA) database." (PMID 34615877, 2021). "We therefore examined the effect of GPR171 on metastasis, specifically cancer cell invasion and migration—a potential role of GPR171 that has not yet been examined." (PMID 26760963, 2016). "To validate GPR171 as an anticancer target, we challenged GPR171-positive cancer cells with GPR171-specific antibodies." (PMID 26760963, 2016). "Authors report here that the G-protein-coupled receptor GPR171 functions as a co-inhibitor of T cell signalling and might serve as a target for cancer immunotherapy." (PMID 34615877, 2021). "Much less is known for P2RY5 and GPR171 and their relation to cancer." (PMID 24662753, 2014). "Though the role of GPR171 in human cancer has not been particularly investigated, we are able to reveal from early clinical trials that GPR171 expression in cancer is upregulated in response to immunotherapy." (PMID 34615877, 2021).
infection (2 papers, 2016 to 2024). The state of being infected such as from the introduction of a foreign agent such as serum, vaccine, antigenic substance or organism. "GPR171 silencing with shRNA #1 or #2 significantly suppressed cell proliferation, reducing the growth of Calu-6 cells to 32.7% (p = 8.4×10−4) and 16.7% (p = 2.2×10−4) of that in control shRNA cells, respectively, 4 days after infection." (PMID 26760963, 2016).
peripheral neuropathy (1 paper, 2021). A disorder affecting the peripheral nervous system. "While we found no alterations in gene expression levels of ProSAAS or GPR171 in the PAG of male or female mice, we found that chemotherapy-induced peripheral neuropathy (CIPN) produces a decrease in GPR171 protein levels in vlPAG of male mice." (PMID 35295419, 2021).
GPR171 also shares sentences with these, for which no sentence is quoted: adenocarcinoma (1 paper); adenocarcinomas of the lung (1); bronchioloalveolar carcinoma (1); coronary artery disease (1); glioma (1); graft versus host disease (1); large cell carcinoma (1); large-cell lung carcinoma (1); metastatic disease (1); metastatic melanoma (1); mucoepidermoid carcinoma (1); neuroblastoma (1); renal fibrosis (1); small cell lung carcinoma (1).